GNAL (G protein subunit alpha L)
Diseases named in the same sentence as GNAL in open-access papers (continued):
Sharing a sentence is not in itself a finding about the gene and the disease.
glioma (continued). "In addition, there is no report about CACNG2, JPH3, TUBB6 (tubulin β 6 class V), NRSN1, FAM19A2, NALCN, CDH18, GNAL on glioma." (PMID 32406502, 2020). "CACNG2, JPH3, TUBB6, NRSN1, FAM19A2, NALCN, GNAL have not been reported in gliomas." (PMID 32406502, 2020). "Findings from the ESTIMATE algorithm revealed significant negative correlations between GNAL expression and StromalScore, ImmuneScore, and EstimateScore, implying that glioma patients with low GNAL expression may not mount strong anti-tumor immune responses that can then induce immune escape." (PMID 38686055, 2024). "In addition, CACNG2, JPH3, TUBB6, NRSN1, FAM19A2, NALCN, GNAL were not reported in glioma." (PMID 32406502, 2020). "Most of them were reported in glioma, CACNG2 JPH3, TUBB6, NRSN1, FAM19A2, NALCN, GNAL have not been reported yet." (PMID 32406502, 2020).
mental disorder (2 papers, 2020 to 2022). A disease that has its basis in the disruption of mental process. "Eight genes are implicated in viral (SEC14L1, JMJD6, SRSF2, TMPRSS2, MX1, MX2) or bacterial (COL8A1, SPIRE1) infections, seven genes (MFSD11, METTL23, CTTNBP2, BACE2, IMPA2, MPPE1 and GNAL) are involved in mental disorders and one gene (MGAT5B) is related to the Golgi complex." (PMID 35581286, 2022).
Parkinson disease (2 papers, 2020 to 2024). A progressive degenerative disorder of the central nervous system characterized by loss of dopamine producing neurons in the substantia nigra and the presence of Lewy bodies in the substantia nigra and locus coeruleus. "Variants in none of the five implicated dystonia genes (TOR1A, SGCE, GNAL, THAP1 and KMT2B) have been reported to cause PD/parkinsonism to date." (PMID 39087914, 2024).
Amoebiasis (1 paper, 2024).
astrocytoma (1 paper, 2024). "Furthermore, the immunohistochemical results showed that the staining score of GNAL protein in patients of astrocytoma and oligodendroglioma are stronger than GBM." (PMID 38686055, 2024).
blepharospasm (1 paper, 2019). "However, a follow-up study reported that all variants detected in GNAL, CIZ1, and TOR2A seemed to be benign in 132 blepharospasm patients." (PMID 32038460, 2019).
Brain Tumor (1 paper, 2024). "The common alteration of GNAL in Brain Tumor PDXs (Mayo Clinic, Clin Cancer Res 2020) cohort was mutation (>6%)." (PMID 38686055, 2024).
depression (1 paper, 2022). "Moreover, a polymorphism study in the alpha subunit found that GNAL gene was associated with major depression." (PMID 35730328, 2022).
endometrial cancer (1 paper, 2021). Primary or metastatic malignant neoplasm involving the endometrium (mucous membrane that lines the endometrial cavity). "It has been observed that as endometrial cancer progresses, expression of CXCL12, GNAL, OPRK1, DRD2, and DRD3 increases while DRD5 and COMT levels are gradually reduced." (PMID 34768458, 2021).
epilepsy (1 paper, 2022). A brain disorder characterized by episodes of abnormally increased neuronal discharge resulting in transient episodes of sensory or motor neurological dysfunction, or psychic dysfunction. "GNAL and ADCY5 genes have not been associated with epilepsy so far." (PMID 36003298, 2022). "While the clinical phenotype associated with ADCY5 and GNAL is characterized by movement disorder in the absence of epilepsy, GNAO1, GNB1, PDE2A, PDE10A, and HPCA have a broader clinical phenotype, encompassing movement disorder, epilepsy, and neurodevelopmental disorders." (PMID 36003298, 2022).
glioblastoma (1 paper, 2024). The most malignant astrocytic tumor (WHO grade IV). "There was a 1% GNAL alteration with a deep deletion in Glioblastoma (CPTAC, Cell 2021)." (PMID 38686055, 2024).
psychosis (1 paper, 2018). "It follows that the epigenetic perturbance may be linked to the development and evolution of psychotic spectrum conditions, as has been suggested for differential methylation of the candidate imprinted GNAL gene with possible maternal effects in the linkage to psychosis." (PMID 29545821, 2018).
Torsion dystonia (1 paper, 2018). Sustained involuntary muscle contractions that produce twisting and repetitive movements of the body. "Although a number of mutations in GNAL linked to isolated torsion dystonia results in a loss of function, many variants were not evaluated for their impact on transduction of GPCR signals." (PMID 30021154, 2018).
torsion dystonia 6 (1 paper, 2016). Primary dystonia DYT6 type is characterized by focal, predominantly cranio-cervical dystonia with dysarthria and dysphagia, or limb dystonia in some cases. "Inherited isolated craniocervical dystonias are rare, and most commonly caused by pathogenic variants in THAP1 (Dystonia-6, DYT6, MIM# 602629) and GNAL (Dystonia-25, DYT25, MIM# 615073) and have adolescent to late adult onset with variable penetrance." (PMID 27919237, 2016).
Torticollis (1 paper, 2023). Involuntary contractions of the neck musculature resulting in an abnormal posture of or abnormal movements of the head. "The GNAL c.1288G>A (p.Ala430Thr) variant was identified for a female patient with CD (left-directed laterocollis, torticollis, and antecollis with platysmal contractions) since the age of 19." (PMID 37445923, 2023). "The GNAL c.677G>T (p.Cys226Phe) variant was identified from a male patient who suffers from left-sided neck pain and right-directed laterocollis, torticollis, and mild retrocollis, as well as periodic “yes–yes” dystonic tremor, since the age of 27." (PMID 37445923, 2023).
cancer (6 papers, 2014 to 2024). A tumor composed of atypical neoplastic, often pleomorphic cells that invade other tissues. "Further analyses using the EPIC algorithm showed that infiltrations of B cells, cancer-associated fibroblasts (CAFs), CD4+ T cells,endothelial, macrophages, NK cells, and other cells were markedly different between GNAL-high and GNAL-low expression groups." (PMID 38686055, 2024). "These associations are likely related to the abnormal GNA15 expression in PDAC cancer cells, whereas GNAL, GNAO1, and GNA14 are preferentially expressed in normal pancreas, which is progressively lost as transformed tissue prevails." (PMID 34290274, 2021). "The novel mutated gene GNAL has the highest between coefficients in HCC samples.The melanoma antigen gene (MAGE) family is a large, highly conserved group of proteins that have been reported to be involved in a variety of cancers in humans." (PMID 35036167, 2021). "Changes in DRD3 levels along with GDNF, GNAL, HRH2, CAV2, and DLG4 were characteristic of G1 cancer." (PMID 34768458, 2021).
tumor (4 papers, 2022 to 2025). "The association of GNAL expression with clinicopathological characteristics, gene mutation landscape, tumor immune microenvironment (TIME), deoxyribonucleic acid (DNA) methylation, and naris-occlusion controlled genes (NOCGs) was performed." (PMID 38686055, 2024). "In our research, we examined the entirety of immune infiltration and analyzed a specific subset of immune-infiltrated cells, ultimately discovering that GNAL was intimately linked to tumor immunity." (PMID 38686055, 2024). "Therefore, we investigated the relationship between GNAL expressions and tumor-infiltrating immune cells." (PMID 38686055, 2024). "Among them, the high expression group of GNAL exhibited a lower estimated IC50, indicating that GNAL can effectively enhance the inhibitory effect of anti-tumor drugs." (PMID 38686055, 2024). "To assess the potential role of GNAL in TIME, we analyzed the effects of GNAL on tumor immunity using the immune infiltration score calculation tool in Sangerbox." (PMID 38686055, 2024).
movement disorder (2 papers, 2022 to 2025). Neurological conditions resulting in abnormal voluntary or involuntary movement, which may impact the speed, fluency, quality and ease of movement. "The dystonic epochs and coordination deficits observed in KCTD5 KO reflect hyperkinetic movement disorder pathology observed in patients with polymorphisms in signal transduction machinery, including DRD2, GNAL, GNAO1, and GNB1." (PMID 40233107, 2025). "Pathogenic mutations in many of these genes (such as DRD2, GNAL, GNAO1, ADCY5, and PDE10A) have been identified in patients with movement disorders (such as dystonia and dyskinesia)." (PMID 40233107, 2025).
adenocarcinoma (1 paper, 2013). A common cancer characterized by the presence of malignant glandular cells. "Multiple genes involved in olfactory transduction and neuroactive ligand-receptor interaction including OR13J1, OR51E2, GNAL, and GRIK1 were also found by this study to be mutated in the adenocarcinoma, suggesting these two classes of genes warrant further investigation." (PMID 23301059, 2013).
infection (1 paper, 2022). The state of being infected such as from the introduction of a foreign agent such as serum, vaccine, antigenic substance or organism. "Although Leptospira was the infection with more genes found in the significant genomic window, few genes are linked to each other (IMPA2, MPPE1, and GNAL—TAF5 and USMG5)." (PMID 35581286, 2022).
neurological disorders (1 paper, 2022). "Indeed, identified genes are implicated in viral (SEC14L1, JMJD6, SRSF2, TMPRSS2, MX1, MX2) bacterial (COL8A1, SPIRE1), and neurological disorders (MFSD11, METTL23, CTTNBP2, BACE2, IMPA2, MPPE1 and GNAL), or in the functions of the Golgi complex (MGAT5B), organelle where viral envelope is occurred." (PMID 35581286, 2022).
GNAL also shares sentences with these, for which no sentence is quoted: pneumonitis (6 papers); cervical dystonia (4); Onset (3); Intellectual disability (2); thyroid (2); Adult onset (1); autoimmune hypophysitis (1); Autoimmunity (1); bipolar disorder (1); bullous pemphigoid (1); colitis (1); colorectal adenoma (1); Dysarthria (1); hereditary spastic paraplegia (1); Huntington disease (1); laryngeal dystonia (1); multiple sclerosis (1); Myoclonus (1); myositis (1); neurodevelopmental disorder (1); Obesity (1); oligodendroglioma (1); Parkinsonism (1); segmental dystonia (1); skin reaction (1).